DAB2 (DAB adaptor protein 2)
Diseases named in the same sentence as DAB2 in open-access papers (continued):
Sharing a sentence is not in itself a finding about the gene and the disease.
lung carcinoma (continued). "We also found that X-ray irradiation up-regulated Dab2 expression in lung cancer cells with hypermethylated Dab2 gene, which lead to increased Axin expression and subsequently decreased expression of β-catenin, as well as Wnt pathway factors including: cyclin D1, MMP-7 and c-myc in LK cells." (PMID 30547821, 2018). "In lung cancer, the overexpression of miR-93-5p inhibited disabled-2 (DAB2) to promote cell growth." (PMID 29361788, 2018). "In vitro/vivo experiments demonstrate that the proliferative and invasive ability were significantly suppressed in lung cancer cells with hypermethylated Dab2 gene promoter with irradiation, but less effective in lung cancer cells with hypomethylated Dab2 gene promoter." (PMID 30547821, 2018). "Herein, we propose that different methylation states of the Dab2 gene promoter correlates with raidosensitivity of lung cancer cells, and that hypermethylation of the Dab2 gene promoter may potentially serve as a molecular pathologic marker for radiotherapy treatment." (PMID 30547821, 2018). "Here, we aim to study if X-ray irradiation can induce de-methylation of the Dab2 gene and subsequently up-regulate its expression, and also to attempt to suppress the malignant biological behavior of and enhance the radiosensitivity in lung cancer cells with hypermethylation of the Dab2 gene." (PMID 30547821, 2018). "Real-time PCR showed that X-ray irradiation up-regulated Dab2 mRNA in lung cancer cells with hypermethylation of the Dab2 gene promoter (LK) but not in lung cancer cells with hypomethylation of the Dab2 gene promoter (SPC)." (PMID 30547821, 2018).
gastric cancer (8 papers, 2010 to 2024). A primary or metastatic malignant neoplasm involving the stomach. "For example, Dab2 rs2255280 is associated with a lower risk of pancreatic cancer, whereas Dab2 rs2243421 is a significant predictor of gastric cancer mortality." (PMID 37361044, 2023). "DAB2 overexpression and knockdown were associated with reduced and enhanced β-catenin expression, respectively, in lung and gastric cancer cells and NIH-3T3 mouse fibroblasts." (PMID 36614139, 2022). "miRNA mediated DAB2 loss has also been reported in Epstein–Barr virus-associated gastric cancer by miR-BART1-3p." (PMID 36614139, 2022). "In SGC gastric cancer cells, knockdown of DAB2 expression was associated with enhanced cell migration and enhanced expression of Wnt signalling components, including β-catenin, GSK3β and cyclinD1." (PMID 36614139, 2022). "In human gastric carcinomas, DAB2+ tumor-associated macrophages correlated with a poor clinical outcome." (PMID 34249086, 2021). "DAB2 is associated with poor prognosis of human lobular breast and gastric carcinomas." (PMID 37693905, 2023). "Disabled homolog 2 (DAB2) is a putative tumor suppressor, but its role in gastric carcinoma (GC), especially in EBV-associated GC, needs to be clarified." (PMID 32025216, 2020). "We then tested the effect of endogenously expressed miR-BART1-3p on DAB2 expression in EBV-infected gastric carcinoma cells using an miRNA inhibitor, miR-BART1-3p(i)." (PMID 32025216, 2020). "In general, EBV-negative gastric carcinoma cell lines showed higher DAB2 expression than did EBV-positive gastric carcinoma cell lines." (PMID 32025216, 2020). "As DAB2 is considered a tumor suppressor in several cancers, we investigated the effect of EBV infection on the expression of DAB2 in gastric carcinoma cells." (PMID 32025216, 2020). "To confirm the role of DAB2 in EBV-positive gastric carcinoma cells, we tested the effect of DAB2 over-expression using pcDNA3.1-DAB2 on apoptosis and cell migration in AGS-EBV cells." (PMID 32025216, 2020). "We compared the steady-state levels of DAB2 mRNA and protein in EBV-negative (MKN45, NCI-N87, SNU216, AGS) and positive (AGS-EBV, SNU719, YCCEL1) gastric carcinoma cell lines." (PMID 32025216, 2020). "In colorectal and gastric cancer cell lines, GATA4 and GATA5 genes and their target genes including DAB2 promoter were found to be hypermethylated, suggesting epigenetic silencing may be responsible for loss of DAB2 protein expression in these cell lines." (PMID 20525238, 2010).
squamous cell carcinoma (7 papers, 2012 to 2025). A carcinoma arising from squamous epithelial cells. "A particular study in head and neck and vulval human squamous cell carcinoma (HSCC) suggested loss of DAB2 expression acts as a switch for TGFβ signalling to change from a tumour suppressor to a tumour promoter role." (PMID 36614139, 2022). "DAB2 promoter methylation was associated with poor cisplatin response and poor OS and PFS in squamous cell carcinomas (SCC) of the head and neck as well as the vulva." (PMID 36614139, 2022). "Squamous cell carcinoma is linked to the expression of MARCKS, CD36, DAB2, ENPEP, and TIMP1." (PMID 40565366, 2025).
colitis (6 papers, 2016 to 2025). Inflammation of the colon. "Although the authors concluded that “Dab2-deficient T cells “were as effective as WT Treg cells in preventing the induction of colitis”, the report provided limited data to support this observation." (PMID 33178208, 2020). "Based on our study with adoptive transfer of Dab2-deficient DCs and DSS colitis, we postulated that DAB2 downregulation would modulate DC function and their response to TLR stimulation." (PMID 30873168, 2019). "Administration of Dab2-deficient DCs (DC2.4Dab2−/− cells) modulated the course of DSS colitis in wild-type mice, enhanced mucosal expression of Tnfa, Il6, and Il17a, and promoted neutrophil recruitment." (PMID 30873168, 2019). "Loss of DAB2 enhanced colitis in mouse models suggesting a role of DAB2 in immune tolerance." (PMID 36614139, 2022). "Dab2 it has been identified as a IFNγ-responsive gene in macrophages and increased mucosal IFNγ is a hallmark of Crohn’s disease and experimental murine colitis." (PMID 33178208, 2020). "Since impaired autophagy in DCs has been also shown to promote intestinal inflammation in mice, which may at least to some extent account for the exacerbating effect of Dab2-deficient DCs in DSS colitis." (PMID 30873168, 2019). "Importantly, consistent with the hypothesis that DAB2 restricts DC immunogenicity, we showed that adoptive transfer of Dab2-deficient DC exacerbated experimental colitis in mice." (PMID 33178208, 2020). "Therefore, the loss of DAB2 in mucosal dendritic cells may be an early contributor to the intestinal inflammation during experimental colitis." (PMID 30873168, 2019). "We evaluated DAB2 expression in the lamina propria DCs in adoptive naïve T cell transfer colitis." (PMID 30873168, 2019). "In additional analysis, it was observed that Dab2-deficient Treg cells failed to alleviate established colitis, suggesting a role of Dab2 in regulating lymphocyte infiltration and accumulation in the colon." (PMID 27933291, 2016). "Here, we describe that Dab2 is highly expressed in colonic CD11b+CD103− DCs and downregulated in the same cell type during experimental colitis." (PMID 30873168, 2019). "It was also found that Dab2 is mainly expressed in intestinal CD11b+ DCs, and the ablated expression of Dab2 in DC2.4 cells (murine immortalized dendritic cells)—measured using the CRISPR-CAS9 system—intensifies exacerbated experimental colitis." (PMID 33800865, 2021). "We show that DAB2 is highly expressed in colonic CD11b+CD103− DCs, a subset known for its capacity to induce inflammatory Th1/Th17 responses in the colon, and is downregulated predominantly in this DC subset during adoptive T cell transfer colitis." (PMID 30873168, 2019). "Another variation of this experiment in the same paper, this time with Treg co-transferred with naïve CD4+CD25-CD45RBhigh T cells, showed that transfer of Dab2−/− Tregs into mice with an established colitis was not effective in reducing the severity of colitis." (PMID 33178208, 2020). "Moreover, we observed that during experimental colitis, DAB2 was downregulated in CD11b+ colonic DCs, regardless of CD103 expression, suggesting that decreased DAB2 expression may indeed be consequential during DC maturation." (PMID 30873168, 2019).
cervical carcinoma (5 papers, 2016 to 2021). A carcinoma arising from either the exocervical squamous epithelium or the endocervical glandular epithelium. "Recently, miR-106b was found to be involved in TGF-β-induced cell migration by targeting disabled homolog 2 (DAB2) in cervical carcinoma." (PMID 33777808, 2021). "miR-106b is up-regulated in cervical cancer through TGF-β1 eliciting migration by down-regulation of Disabled Homolog 2, Mitogen-Responsive Phosphoprotein (Drosophila) (DAB2) via 3′UTR." (PMID 28216603, 2017). "miR-106b is regulated by TGF-β1 and contributes to cell migration by targeting DAB2 in cervical carcinoma." (PMID 26769181, 2016). "The mRNA expression of DAB2 in 19 cervical carcinoma samples was significantly reduced, by 79.1 %, to 0.21 ± 0.03, as compared with normal cervical tissues (P < 0.01)." (PMID 26769181, 2016). "The expression of DAB2 was low in cervical cancer tissues, and negatively correlated with miR-106b expression." (PMID 26769181, 2016). "In general, miR-106b is involved in TGF-β1-induced cell migration by targeting DAB2 in cervical carcinoma." (PMID 26769181, 2016). "Immunohistochemistry revealed reduced DAB2 protein level in cervical cancer tissue." (PMID 26769181, 2016). "miR-106b was involved in TGF-β1-induced cell migration by targeting DAB2 in cervical carcinoma." (PMID 26769181, 2016). "Our data suggest that the TGF-β1/miR-106b/DAB2 axis may be involved in the pathogenesis of cervical carcinoma." (PMID 26769181, 2016). "In this study, DAB2 was first identified to have low expression in cervical cancer." (PMID 26769181, 2016). "The TGF-β1/miR-106b/DAB2 axis could provide further insight into the pathogenesis of cervical carcinoma, and miR-106b could be a biomarker and potential therapeutic target in cervical cancer." (PMID 26769181, 2016). "The TGF-β1/miR-106b/DAB2 axis is involved in the migration of cervical cancer cells." (PMID 26769181, 2016). "In addition, DAB2 was identified as a target of miR-106b in cervical cancer." (PMID 33945993, 2021). "DAB2, a predicted target gene of miR-106b, was inhibited by TGF-β1 partly through miR-106b and was involved in TGF-β1-induced cervical cancer cell migration." (PMID 26769181, 2016).
nasopharyngeal carcinoma (5 papers, 2010 to 2022). A carcinoma arising from the nasopharyngeal epithelium. "We aimed to investigate the possible tumour suppressor effect of DAB2 in nasopharyngeal carcinoma (NPC)." (PMID 20525238, 2010). "The involvement of DAB2 in nasopharyngeal carcinoma (NPC) has not been addressed before." (PMID 20525238, 2010).
prostate carcinoma (5 papers, 2011 to 2023). A carcinoma that arises from epithelial cells of the prostate gland. "Later, DAB2 overexpression was found to directly inhibit prostate cancer cell proliferation by down-regulating AKT and ERK kinases." (PMID 37510211, 2023). "Loss of DAB2 was associated with MAPK activation and enhanced cell proliferation, migration and therapy resistance in C4-2 prostate cancer cells." (PMID 37815603, 2023). "Enhanced proliferation and in vivo tumorigenicity by DAB2 has also been observed in urothelial and prostate cancer highlighting the need for further studies." (PMID 37815603, 2023). "MVIBD consists of two known Myosin VI binding sites fused in tandem, one from Optineurin, a protein that is associated with amyotrophic lateral sclerosis and a second from Disabled homolog 2 (DAB2), which has been associated with prostate cancer." (PMID 21390300, 2011). "Recent studies have suggested that miR-93 promotes prostate cancer progression/metastasis by suppressing DAB2 to activate the Akt/ERK1/2 pathway, and that the upregulation of DAB2 and inactivation of Akt/ERK1/2 may be a potential therapeutic target for prostate cancer green tea polysaccharide." (PMID 37510211, 2023).
atherosclerosis (4 papers, 2020 to 2023). A disease characterized by the build-up of fatty material and calcium deposition in the arterial wall resulting in partial or complete occlusion of the arterial lumen. "V55 increased expression of Socs3 and Dab2 genes (inhibitors of cytokine signaling and NF-κB pathway), Apoe (associated to atherosclerosis control), Igf1 (encoder a protein with analogous effects to insulin) and Fgf10 (fibroblasts growth factor)." (PMID 35631379, 2022). "In other studies, analysis of Dab2-deficient bone marrow revealed increased systemic inflammation and cytokine expression, which led to liver injury; however, the effect of Dab2 deletion in atherosclerosis has yet to be determined." (PMID 33363178, 2020). "Moreover, (3S)-vestitol up-regulated the expression of Socs3 and Dab2 genes (inhibitors of cytokine signaling and the NF-κB pathway), Apoe (related to atherosclerosis control), Igf1 (encoder a protein with analogous effects to insulin) and Fgf10 (fibroblasts growth factor)." (PMID 35631379, 2022). "In another study, quercetin attenuated the progression of atherosclerosis by regulating dendritic cell maturation by upregulating Dab2 expression." (PMID 33363178, 2020). "Interestingly, another report showed that quercetin-mediated up-regulation of Dab2 expression attenuates the atherosclerosis." (PMID 36769293, 2023). "Hence, Dab2 is considered as a new anti-atherosclerosis therapeutic." (PMID 36769293, 2023).
bladder cancer (4 papers, 2015 to 2023). "siRNA mediated knockdown of DAB2 expression in UM-UC-3 bladder cancer cells was associated with reduced tumour formation in vivo and subsequent enhanced expression of EMT marker KRT14 and reduced expression of the mesenchymal to epithelial transition (MET) marker occludin (OCLN)." (PMID 36614139, 2022). "A study in bladder cancer found secreted factors from DAB2 overexpressing stromal cells promoted EMT in UM-UC-3 cells whilst DAB2 knockdown inhibited EMT." (PMID 37815603, 2023). "In grade 3, stage 1 (T1G3) bladder cancer there was a 2.85 fold increase in DAB2 expression in patients that progressed versus patients that did not." (PMID 36614139, 2022). "One of its regulators, DAB2, has also been reported to be prominent in advanced stages of urothelial cancers, where a decreased expression of the molecule could be observed in metastatic stages, and has been associated with high probabilities of recurrence and bladder carcinoma mortality." (PMID 25569276, 2015).
colorectal cancer (4 papers, 2017 to 2023). A primary or metastatic malignant neoplasm that affects the colon or rectum. "Furthermore, several genes included in this list have previously been linked to colorectal cancer (i.e. Id1, Lgals9, Stat2, and Dab2)." (PMID 27129739, 2017). "The analysis of DAB2 gene expression data exported from the TCGA Colon and Rectal Cancer (COADREAD), which contained 736 colorectal cancer samples, has found lower DAB2 gene expression in R-CRC, in comparison to the L-CRC (p < 0.0001)." (PMID 37510211, 2023). "Disabled homolog 2 (DAB2), as a member of the disable gene family, has been proven to function as a tumor suppressor that plays an crucial role in the occurrence and progression of various tumors, including colorectal cancer and epithelial ovarian cancer." (PMID 34109210, 2021). "Several studies investigated the role of DAB2 and its interactive protein (DAB2IP) in colorectal carcinoma." (PMID 37510211, 2023).
hepatocellular carcinoma (4 papers, 2022 to 2024). A malignant tumor that arises from hepatocytes. "We found that PPT1 and FTL were highly expressed in hepatocellular carcinoma cell lines, while DAB2 and SAT1 were highly expressed in human hepatocytes." (PMID 37693905, 2023). "Methylation of DAB2 promoter was significantly increased in hepatocellular carcinoma patients with OS survival less than 3 years." (PMID 36614139, 2022). "miR-106b was also shown to enhance proliferation and migration of hepatocellular carcinoma (HCC) cells, which was inhibited by DAB2 expression." (PMID 36614139, 2022).